NOTCH1 (notch receptor 1)
Diseases named in the same sentence as NOTCH1 in open-access papers (continued):
Sharing a sentence is not in itself a finding about the gene and the disease.
tumor (continued). "In this study, we report that the Notch1/CD73 axis plays a role in cellular cisplatin sensitivity, but how it affects the tumor immune microenvironment will need to be further evaluated." (PMID 37391408, 2023). "This has important clinical relevance since the authors also demonstrated a strong correlation between Notch1 and immunosuppressive cells such as CD68+CD163+TAMs and immune checkpoint molecules in patient HNSCC tumor samples." (PMID 38269089, 2023). "NOTCH1 expression in T-cell development depends on plant homeodomain finger protein 6 (PHF6), which plays a tumor suppressor role in T-ALL." (PMID 38812997, 2023). "Compared with colorectal T cells from healthy individuals, the expression of PD-1 and Notch signaling molecules (NOTCH1, NOTCH2, HES1, and HES5) was elevated in tumor-infiltrating CD8+ T cells from CRC patients." (PMID 37131214, 2023). "In addition, treatment of the 143B OS mouse model with IL‐24 revealed inhibition of the tumor growth rate and downregulation of Notch 1, Hes 1, and β‐catenin expression in xenograft tumor tissues, suggesting that IL‐24 may be a new target to improve long‐term survival of patients with OS." (PMID 37441462, 2023). "The expression of NOTCH1 and NOTCH3 mRNA and fold changes in monocultures of UT-SCC-42B, UT-SCC-24B, and CAFs, compared to 3D cocultures of different tumor cells with varying ratios to CAFs (3:1, 1:1, 1:3), was performed by qRT-PCR." (PMID 38001580, 2023). "While the multitude of mostly suppressive variants of NOTCH1 shows that it acts as a tumor regulator, several investigators reported that activation of NOTCH can promote proliferation, prevent apoptosis, and stimulate angiogenesis, suggesting that NOTCH1 may occasionally act like an oncogene." (PMID 37205904, 2023). "Further in vivo studies suggest that NOTCH1 and NOTCH3 inhibition reduces cancer cell proliferation and tumour size." (PMID 37605966, 2023). "The diffusible gas carbon monoxide altered TME and impeded tumor growth via regulating MAPK/Erk1/2 pathway, Notch-1 pathway, HO-1 and CD86 expressions in lung cancer." (PMID 37033636, 2023). "It has been described a dual role for the Notch receptor (Notch 1–4)-ligand (JAG1, JAG2, DLL1, DLL3 and DLL4) pathways as oncogenic or tumor suppressors." (PMID 36745330, 2023). "Mechanistically, activation of Notch1 in epithelial cells promoted the secretion of TGF-β into the TME, increased the recruitment of TGF-β-dependent neutrophils, and inhibited the anti-tumor function of CD8+ T cells." (PMID 37131214, 2023). "The Notch1 knockout tumours were particularly enriched among tumours from tumour clusters IV and V, consistent with the depletion of MSCC phenotype tumours from this cohort and the enrichment of tumour clusters I and III with tumours of this histotype." (PMID 37686600, 2023). "It has been shown that Notch1 inhibition in GBM xenografts reduces the hypoxic fraction and delays tumor progression, suggesting a potential mechanism whereby Notch1 downregulation radiosensitizes GBM cells." (PMID 36362359, 2022). "The disruption of the NOTCH signaling pathway with NOTCH1 silencing or treatment with DAPT, a γ-secretase inhibitor, reduces tumor-derived ECs in GBM organotypic cultures." (PMID 36294763, 2022). "Second, coactivation of NOTCH1 and MYC increases the frequency of NICD1-induced adenoma formation and enables tumor progression and metastases in a mouse model." (PMID 35332121, 2022).
tumor (continued). "We further investigated the anti-tumor effect of chetomin, an inhibitor of the HIF pathway, in U251-MG xenograft models using the same regimen as that used for the doxycycline sh-Notch1 xenograft models." (PMID 36183290, 2022). "This suggested that NOTCH1 plays a role as tumour suppressor in AML, furthermore, a novel pathway that activates NOTCH1 for inhibiting cell growth was identified." (PMID 35350997, 2022). "As to concern clinical and pathological correlations, NOTCH1, NEUROD1, MYCL1, and YAP1 were found significantly correlated with tumor stage." (PMID 36121500, 2022). "Consistent with this, the present in vivo data indicated that ablating HIF-1α by silencing Notch1 as a guard-molecule or by treating with chetomin, a HIF pathway inhibitor, induced significant anti-tumor effects in GBM xenograft models." (PMID 36183290, 2022). "Several publications suggested that NOTCH1 has a bimodal role in HNSCC, therefore acting as a tumor suppressor and oncogene depending on the context." (PMID 35205828, 2022). "Given that GSK3β inhibition increases NOTCH1 signaling and CLL cell survival, and NOTCH1 signaling is oncogenic in CLL, we suggest that GSK3β has a tumor suppressor role in CLL." (PMID 36050315, 2022). "It targets Notch1, L1CAM, MMSET and thus inhibits EC cells migration, invasion, and EMT in vitro as well as tumor growth in vivo." (PMID 36335210, 2022). "Taken together, our results indicate that A2AR activation suppresses CD8+ T-cells function, at least in part, through promoting Notch1 degradation, and A2AR blockade restores Notch1, T-cell function and anti-tumor potential." (PMID 36090975, 2022). "Silencing Notch1 signaling using a doxycycline-inducible Notch1 RNA-interfering system or treatment with chetomin, a HIF pathway inhibitor, retarded tumor development with a significant anti-cancer effect in a murine U251-xenograft model." (PMID 36183290, 2022). "For example, overexpressed Notch-1 promotes epithelial-mesenchymal transition (EMT), and consequently, invasion and migration of tumor cells in ovarian, breast, and lung cancers, while in NSCLC, downregulated Notch-3 plays a tumor-suppressive role." (PMID 36143328, 2022). "Immunostaining and flow cytometry revealed that the nuclear Notch1 ICD and Hey1 levels, respectively, were enhanced in the GIT1 knockdown tumours compared to the control tumours." (PMID 35318302, 2022). "When compared to their control counterparts, TRPM7-silenced tumor samples had significantly lower expression of NFATC2, Notch1, and P-MEK proteins." (PMID 35771152, 2022). "Taken together, these data demonstrated that activation of Notch1 is required for p65/p66-induced EMT and tumor cell migration." (PMID 35457181, 2022). "Particularly, Crenigacestat was able to selectively inhibit NOTCH1 in vitro and in the PDX model, reducing tumor progression by blocking new vessel formation in the surrounding desmoplastic reaction tissue." (PMID 35457006, 2022). "Jagged 1 in turn induces NOTCH1 and perhaps NOTCH3, forming a Jagged-involved tumor-stromal paracrine signaling loop." (PMID 36517618, 2022). "NOTCH1 is expressed in nodal and cutaneous ALCL primary tumour tissues via an interaction with its ligand Jagged1 on ALCL cells which promotes tumour cell proliferation while preventing apoptosis." (PMID 35681778, 2022).
tumor (continued). "The next question then becomes, what is happening with the pro‐angiogenic factors, Notch1 and VEGFR2, within the tumour region." (PMID 34910361, 2022). "Each of the LEP, NOTCH1, SPRY1, PPARG, ID2, and CIDEA genes is also involved in tumor development in humans." (PMID 35395810, 2022). "Notch1 has been demonstrated to be dysregulated in CRC, correlating with poor survival, CSC phenotype and EMT, thus resulting in tumor progression." (PMID 34959725, 2021). "To examine the effects of Notch1/TAZ axis on glycolysis in vivo, we used 18FFDG micro-PET (positron emission tomography) scans to measure glucose uptake in tumor xenografts in nude mice." (PMID 34482375, 2021). "Together, these data indicated that SNHG22 promotes GC progression through elevating Notch1 and recruiting EZH2 to suppress tumor suppressive genes in vivo." (PMID 34663788, 2021). "Colocalization of NOTCH1 and HER3 on the centrally-located differentiated neoplastic cells within the infiltrative tumor nests was also discerned in 51% of cases of our enrolled cohort." (PMID 34465724, 2021). "Administration of particles suppressed tumor growth and induced tumor cell apoptosis through targeting CD44 and the Notch-1 signaling pathway." (PMID 34198550, 2021). "Drawing insights into the functions of these genes, several tumor proliferation-related genes (EGFR, NOTCH1, and MAP2K1) and the anti-apoptosis related genes (BCL2L1, XIAP) were detected." (PMID 33637972, 2021). "A strong upregulation of Notch1 and Notch intracellular domain (NICD), i.e., the cleaved and active form of Notch1, was found in whole cell lysates of tumor spheres at serial passages, along with increased levels of Notch1 effectors, such as RBPSUH and c-Myc." (PMID 33922104, 2021). "Apart from KRAS and PIK3CA, other genes preferentially altered in the right-sided primary tumor sites, such as PRKDC, ERBB3, BCLAF1 and NOTCH1, have been reported to be correlated with poor prognosis or migration in CRC." (PMID 34281583, 2021). "We also observed that tumor suppressors, including KLF12, PRKG1, TRPS1, NOTCH1, and RORA, were downregulated in the HSPA8high group." (PMID 33926391, 2021). "Anisomycin can inhibit angiogenesis, proliferation and invasion of tumor cells by blocking the PI3K/Akt pathway and Notch1 pathway." (PMID 35087829, 2021). "For instance, studies show that Notch receptors such as Notch1 are overexpressed in PDAC, with in vitro studies pointing at a reduction of tumor-promoting factors by e.g., Notch4 inhibition." (PMID 33498866, 2021). "A lot of studies have disclosed the expression of NOTCH components in tumor contexture, especially DLL4/NOTCH1, being upregulated by VEGF." (PMID 34940041, 2021). "Notch1 and DNMT3A are not only related to the proliferation of tumor cells, but also to the regulation of invasion and metastasis, which can influence patient prognosis." (PMID 35087829, 2021). "In a cohort of primary GC tissues, NOTCH1-3 were highly expressed compared with normal gastric tissues according to GENT (Gene Expression across Normal and Tumor tissue) dataset." (PMID 33452458, 2021). "Meanwhile, tumor suppressors, including KLF12, PRKG1, TRPS1, NOTCH1, RORA, were downregulated in the HSPA8high group." (PMID 33926391, 2021). "However, METTL14 has been identified to be decreased in bladder cancer and related tumor initiating cells (TICs), knockdown of which promotes the cell proliferation, self-renewal, metastasis and tumor initiating capacity through reducing the stability of m6A-modified Notch1 mRNA202." (PMID 33611339, 2021). "In short, it appears that tumour angiogenesis in HNSCC simultaneously involves both the HIF-1α and Notch1 pathways." (PMID 34944837, 2021).
tumor (continued). "Tumor-stroma ratio (TSR), microvessel density (MVD) and endothelial Notch 1 (EC Notch 1) were investigated for correlation with imaging parameters." (PMID 34642389, 2021). "Consequently, in vivo high-dose RT, in combination with inhibition of Notch1 signalling, resulted in a significant reduction in tumour vessel endothelial cell coverage in comparison to high-dose RT alone, suggesting Notch1 signalling may protect tumour vessels from radiation-induced damage." (PMID 33467153, 2021). "Endothelial Notch1 signaling upregulates VCAM1 expression, which promotes the adhesion of tumor cells to the endothelium, extravasation and lung colonization, as shown by using VCAM1-blocking antibodies." (PMID 34073394, 2021). "Studies of prostate cancer have shown increased marker expression of EMT and Notch1, including vimentin, N-cadherin, ZEB1 (Zinc-finger E-box binding homeobox), NF-κB, and PDGF-D in tumor cells." (PMID 33670230, 2021). "For example, one study identified two tumour initiating cell subsets within the BCSC population and demonstrated active Notch1 signalling in the more proliferative, invasive and metastatic subpopulation (CD44+/CD24low) but not the other (CD44+/CD24–)." (PMID 34295896, 2021). "Adherent cells (parental) and tumor spheres (TS) from NSCLC H1975 cells and patient-derived CD133-positive cells were tested for EGFR and Notch1 signaling cascade." (PMID 33922104, 2021). "In particular, genetic blockade of Notch1 combined with PI3K or TORC1/2 inhibition abrogates the increase of BCSC markers, mammosphere formation, and in vivo tumor-initiating capacity, thus eradicating drug-resistant BCSCs." (PMID 35582386, 2021). "Silencing NOTCH1 partially normalizes CAF gene expression, impairs cSCC cell growth in co-culture, and reduces tumor size, macrophage infiltration, and angiogenesis in xenograft." (PMID 34553848, 2021). "Likely, the influence of the tumor and the TME results in a genetic or epigenetic facilitation of Notch1 inactivation." (PMID 33705467, 2021). "Other reported findings impart evidence that NOTCH1 and DLL4 were overexpressed within the tumor vasculature and upregulation of NOTCH/c-MYC activates the AKT pathway via PTEN phosphorylation; consequently, the NOTCH activation intensifies PI3K/mTOR activity." (PMID 34940041, 2021). "Particularly, miR-34a has been confirmed to be a well-defined tumor suppressor which could persuade the cell apoptosis, the cell cycle arrest at G1 phase and also restrain the migration of tumor cells by decreasing the expression of Bc1-2, Notch-1, survivin, CD44 and the cyclin family." (PMID 34443415, 2021). "The authors showed that Notch1/Jagged1 signaling activation occurs through Gal3 modulation, and in turn, promoted HUVEC spheroid sprouting in an in vitro model of tumor angiogenesis." (PMID 34222228, 2021). "Based on the GEPIA database, we observed that expression levels of Notch1, CDK5, p35, and p39 are higher in PDAC tumor tissues than in normal tissues." (PMID 33960694, 2021). "Cancer stem cells (CSCs), a subpopulation of cells with the capacity for maintaining tumor self-renewal, promoting recurrence and metastasis, have been identified through the expression of several cellular markers such as ALDH1 and Notch1." (PMID 33854547, 2021). "Moreover, strong immunoexpression of Notch1 was useful in cases of some clinicopathological variables of patients with poorly differentiated OSCCs, once again revealing their participation in oral neoplasms according to the pattern of tumor cell differentiation." (PMID 33854547, 2021). "FBXW7 is a key substrate recognition subunit of the SCF complex that acts as a tumor suppressor gene by controlling the proteasome-mediated degradation of oncoproteins, such as c-MYC, MCL1, Notch1/4, cyclin E, and mTOR." (PMID 33676554, 2021). "Ability of PANC-1 and AsPC-1 cells to form tumor spheres was enhanced by SNHG7 overexpression and repressed by Notch1 downexpression." (PMID 34631547, 2021).
tumor (continued). "Several different regulatory factors, including Notch-1 and CCL5, are reportedly involved in the molecular mechanism of tumor-endothelial trans-differentiation." (PMID 33102474, 2020). "Finally, the inhibition of NOTCH1 on the basis of the use of molecules that block its proteolytic cut (γ-secretase inhibitors (GSIs)) or humanized antibodies (OMP-52M51) may also be re-activated by tumor suppressors inhibited by its activity." (PMID 32182763, 2020). "On the other hand, a larger Notch1 decoy, N11–24, recapitulated the effects of inhibiting either JAG1 or DLL4 or both, depending on the tumor microenvironment and in vitro angiogenesis model used." (PMID 32922403, 2020). "We have shown that the overexpression of AKT and thus Notch1 signaling increase CRC cell proliferation and tumor burden." (PMID 32630477, 2020). "Particularly, previous investigations indicated that NOTCH1 and its target gene HES1 were markedly increased in GSCs, leading to tumor invasion and recurrence of GBM, and Notch1 overexpression was also associated with low overall survival." (PMID 32526957, 2020). "Interestingly, we found an enrichment of cluster 4 in tumour of P1207 without NOTCH1/NOTCH2/FBXW7 mutations, but it is not known whether or not P1207 had mutations in other members of the Notch signalling pathway." (PMID 32924269, 2020). "Further, ST3Gal IV overexpression increased the Jagged1, Notch1, Hes1, Hey1 and p21 expression, meanwhile, decreased the expression levels of CyclinD1, CyclinE1, CDK2 and CDK4 in xenograft tumor tissues." (PMID 33598419, 2020). "In hepatocellular carcinoma cells, ROS-induced nucleus translocation of NRF2 can activate the Notch1/Snail signaling pathway to accelerate EMT and metastasis of tumor cells." (PMID 33274006, 2020). "The result of immunohistochemistry revealed that after the inhibition of SNHG3 expression, Notch1-, Notch2- and Notch3-positive cells in MCF-7 xenograft tumor increased (p < 0.05)." (PMID 32883233, 2020). "Concomitant expression of Notch 1 intracellular domain (N1ICD), partially rescued this inhibition of tumor growth." (PMID 32555153, 2020). "The TNFα-induced increase of tumor cell motility and CXCL8 production by contact TNBC co-cultures with MSCs were inhibited by GSI, and direct involvement of Notch1 was demonstrated in up-regulating CXCL8 production." (PMID 32605277, 2020). "Notch1 expression was also increased and Ikaros/IRF8 expression decreased in the DN2 population isolated from tumor-bearing IL-10−/− mice as compared to wild-type tumor-bearing mice." (PMID 32582141, 2020). "This tumor can be subdivided into a common conventional-type ACC and a solid-type ACC: NOTCH1 (47% vs 7%), NOTCH2 (13% vs 0%), and NOTCH3 (7% vs 0%) were clearly more frequent in solid-type ACC than in conventional-type ACC." (PMID 32210163, 2020). "SCNVs shared within the tumor-organoid pairs encompassed regions including BC-relevant genes, such as the tumor suppressor genes APC, PTEN, and ARID1; the oncogenes NRAS, and NOTCH1." (PMID 33371412, 2020). "Our findings indicated that following TNFα stimulation of tumor-stroma co-cultures, NF-κB activation has led to CXCL8 induction, partly through a Notch1-dependent process." (PMID 32582148, 2020). "IL-10 was also likely responsible for suppressing the Notch1 expression in DN2a T cells, since notch 1 expression in DN2 T cells and transition from DN2 to DN3 was normalized in tumor-bearing IL-10−/− mice." (PMID 32582141, 2020). "These aggregate data suggest that the reciprocal regulation of Notch1 and Ikaros in DN2 subpopulations in the thymus of tumor-bearing mice instigates early arrest of T-cell development at the DN2a stage and its diversion toward the DC lineage." (PMID 32582141, 2020). "We have previously reported novel mutations in the WD40 domain of FBXW7 preventing degradation of NOTCH1 in ATL cells and decreased in vivo tumor growth by blockade of NOTCH1-dependent growth of ATL cells." (PMID 32907612, 2020).